PGR (progesterone receptor)
Diseases named in the same sentence as PGR in open-access papers (continued):
Sharing a sentence is not in itself a finding about the gene and the disease.
breast cancer (continued). "In this patient, immunochemical staining was negative for PAX8, p40, ER, and PgR, ruling out thymic carcinoma and breast cancer metastasis." (PMID 38627639, 2024). "The MCF-7 cell line represents estrogen–progesterone receptor-positive breast cancer, while AMJ13 is an estrogen–progesterone receptor-negative breast cancer cell with weak or absent expression of her-neu 2 expression." (PMID 39281317, 2024). "According to the expression levels of estrogen receptor (ER), progesterone receptor (PR), human epidermal growth factor receptor 2 (HER2), and Ki67, breast cancer is classified into Luminal A, Luminal B, HER2 over-expression and Basal-like (Triple negative) sub-types." (PMID 38245723, 2024). "Triple-negative breast cancer (TNBC) is one of the subtypes of breast cancer classified by a lack of protein expression of oestrogen receptor (ER), progesterone receptor (PgR) and human epidermal growth factor receptor 2 (HER2)." (PMID 38539422, 2024). "Triple negative Breast Cancer (TNBC) is a histological subtype of breast cancer (BC) characterized by the immunohistochemical lack of expression (< 1%) of estrogen receptor (ER), progesterone receptor (PgR), and human epidermal growth factor receptor 2 (HER2)." (PMID 38464390, 2024). "Triple-negative breast cancer (TNBC) accounts for 10–15% of all breast cancers and is characterized by the lack of expression of estrogen receptor (ER), progesterone receptor (PR), and human epidermal growth factor receptor 2 (HER2)." (PMID 39201277, 2024). "It is interesting therefore that the progesterone receptor has been shown to drive tumour growth and metastasis in the absence of ER activity in breast cancer." (PMID 39088439, 2024). "Triple‐negative breast cancer (TNBC) represents the most aggressive histological subtype of breast cancer, and is characterised by an absence of estrogen receptor (ER), progesterone receptor (PR) and HER2 expression." (PMID 38372449, 2024). "Triple-negative breast cancer (TNBC) is the most malignant subtype of breast cancer, which is defined as estrogen receptor (ER)-negative, progesterone receptor (PR)-negative, and human epidermal growth factor receptor type 2 (HER2)-negative disease." (PMID 38217030, 2024). "Based on the expression of estrogen receptor (ER), progesterone receptor (PR), and human epidermal growth factor receptor 2 (HER2), breast cancer is categorized into several subtypes, including hormone receptor (HR)-positive, HER2-positive, and triple-negative breast cancer (TNBC)." (PMID 38539508, 2024). "Breast cancer is classified based on the combinational presence/absence of three receptors—estrogen receptor (ER), progesterone receptor (PR), and human epidermal growth factor receptor 2 (HER2)." (PMID 39125761, 2024). "Moreover, breast cancer cells with expression of ESR, PGR, or GPER showed higher levels of TET3 after 4-HT treatment, but in triple-negative cells (MDA-MB-231), TET3 was deceased upon 4-HT supplementation." (PMID 39201247, 2024). "Triple-negative or basal-like breast cancer is ER-negative, progesterone receptor-negative, and HER-2-negative." (PMID 38672654, 2024). "Based on molecular markers such as the estrogen receptor (ER), progesterone receptor (PR), and human epidermal growth factor receptor 2 (HER2), breast cancer can be classified into three main subtypes: hormone receptor (HR)-positive, HER2-positive, and triple-negative breast cancer (TNBC)." (PMID 39524172, 2024). "Breast cancer is categorized into four subtypes based on the presence or absence of hormone receptors—estrogen receptor (ER) and progesterone receptor (PgR)—which serve as therapeutic targets, as well as the expression of HER2." (PMID 39519118, 2024).
breast cancer (continued). "Triple-negative (negative for ER/PgR/HER2) breast cancer (TNBC) can be molecularly classified as basal-like, luminal-AR (androgen receptor), immune-activated, and claudin-low." (PMID 37934318, 2024). "Notably, First-order Features, such as Mean Absolute Deviation, Minimum, and Uniformity, exhibited strong correlations with ER, PgR, Ki67, and HER2, indicating their potential as reliable indicators of tumor characteristics and behavior in breast cancer." (PMID 39518625, 2024). "TNBC is a subtype of breast cancer characterized by a lack of expression of three key receptors: estrogen receptor (ER), progesterone receptor (PR), and human epidermal growth factor receptor 2 (HER2)." (PMID 38339348, 2024). "In clinical practice, the molecular subtyping of breast cancer (BC) relies on immunohistochemistry (IHC) to measure the protein expression of estrogen receptor ER/ESR1, progesterone receptor PR/PGR, human epidermal growth factor receptor 2 HER2/ERBB2, and marker of proliferation Ki67/MKI67." (PMID 38337757, 2024). "In breast cancer, relying solely on the expression of ER and PgR is unlikely to determine the most suitable treatment approach for a patient." (PMID 38514638, 2024). "Triple-negative breast cancer (TNBC), which accounts for approximately 15% of all breast cancers, is highly aggressive and characterized by the absence of estrogen receptor (ER), progesterone receptor (PR), and human epidermal growth factor receptor 2 (HER2)." (PMID 38449391, 2024). "Here, our results revealed ME1 expression was significantly upregulated in breast cancer, especially in patients with oestrogen receptor/progesterone receptor-negative and human epidermal growth factor receptor 2-positive breast cancer." (PMID 38445776, 2024). "Triple-negative breast cancer (TNBC) accounts for 15–20% of breast cancers, which is characterized by a lack of over-expression of estrogen receptor (ER), progesterone receptor (PR), and human epidermal growth factor receptor 2 (HER2)." (PMID 38194043, 2024). "Breast cancer is mainly classified into three subtypes based on the presence or absence of estrogen receptor (ER), progesterone receptor (PR), and human epidermal growth factor receptor 2 (HER2)." (PMID 38167105, 2024). "It is a luminal A breast cancer cell line, isolated from the pleural effusion of a 69-year-old woman with metastatic disease and is ER and progesterone receptor (PR) positive, and HER2 negative." (PMID 38408073, 2024). "In TNBC, the three main breast cancer tumor markers: estrogen receptor (ER), progesterone receptor (PR), and Her2 are all negative." (PMID 39030557, 2024). "Triple-negative breast cancer (TNBC) is a subtype of breast cancer characterized by the absence of estrogen receptor (ER), progesterone receptor (PR) and human epidermal growth factor 2 (HER2) expression." (PMID 38831379, 2024). "Breast cancers are categorized by the presence or absence of cellular markers that are used to guide treatment: estrogen receptor (ER), progesterone receptor (PR), and human epidermal growth factor 2 (HER2)." (PMID 39069534, 2024). "TNBC is a subtype characterized by the absence of estrogen receptor, progesterone receptor, and human epidermal growth factor receptor 2 expression and is considered one of the most lethal subtypes of breast cancer." (PMID 38755678, 2024). "All patients had mTNBC, of whom 26% had non-triple-negative primary breast cancer (estrogen receptor and/or progesterone receptor ≥ 10%) with proven triple-negative metastatic relapse." (PMID 38600429, 2024). "About 15% of breast cancers do not express estrogen (ER) or progesterone receptor (PgR) expression (≤ 1%) or show human epidermal growth factor receptor 2 (HER 2) overexpression or amplification." (PMID 38238552, 2024). "Higher soy consumption reduced breast cancer development in post-menopausal women, especially ER- and ER-/PgR-negative subtypes." (PMID 38254795, 2024).
breast cancer (continued). "Triple-negative breast cancer (TNBC) is a highly concerning subtype of breast cancer that is characterized by the absence of key receptors, including the estrogen receptor (ER), progesterone receptor (PR), and human epidermal growth factor receptor 2 (HER2)." (PMID 39135924, 2024). "Luminal A breast cancer shows estrogen and progesterone receptor expression, does not express HER2, and is characterized by a low level of the proliferation marker protein Ki-67." (PMID 39001543, 2024). "TN breast cancer is characterized by the absence of these receptors (ER, progesterone receptor or HER2), and it is characterized by a higher relapse rate and a decreased survival rate 3–5 years after diagnosis." (PMID 39195531, 2024). "The alterations in the methylation profile in breast cancer may also occur in specific genes, including ESR, PGR, or HER2, affecting their expression, thus representing a different response to endocrine/hormonal therapies." (PMID 39201247, 2024). "Triple-negative is an aggressive subtype of breast cancer (BC) characterised by the absence of oestrogen receptor (ER), progesterone receptor (PR), and HER2 expression." (PMID 39338198, 2024). "Triple-negative breast cancer (TNBC) represents a subtype of breast cancer characterized by the absence of estrogen receptor (ER), progesterone receptor (PR), and human epidermal growth factor receptor 2 (HER2) expression." (PMID 38747288, 2024). "Triple-negative breast cancer (TNBC) is a highly aggressive and clinically challenging subtype of breast cancer, lacking the expression of estrogen receptor (ER), progesterone receptor (PR), and HER2/neu." (PMID 39744000, 2024). "Additionally, cases of hormonal triple-negative breast cancer (estrogen-receptor (ER), progesterone-receptor (PR), and human epidermal growth factor receptor-2 (HER-2)) are seen in only 10% of breast cancers." (PMID 39717332, 2024). "Notably, three predominant biomarkers—estrogen receptor (ER), progesterone receptor (PR), and HER2—have become essential in clinical practice for identifying intrinsic breast cancer subtypes and guiding treatment decisions." (PMID 38509525, 2024). "Breast cancer receptor status was negative for the estrogen receptor, negative for the progesterone receptor, and positive for HER2." (PMID 39238765, 2024). "The lack of progesterone receptor expression was reported as the factor for poor treatment outcome in breast cancer." (PMID 39596349, 2024). "The results from our spatial and single‐cell analyses were further supported by a public ER+ breast cancer single‐cell dataset and protein‐based dual immunohistochemistry (IHC) of SC31 examining important luminal cancer markers (i.e., ER, progesterone receptor and Ki67)." (PMID 38282415, 2024). "Disparities in estrogen receptor (ER), progesterone receptor, human epidermal growth factor receptor 2 (HER2), and Ki67 proliferation indices facilitate the categorization of breast cancer into four principal subtypes: luminal A, luminal B, HER2-positive, and triple-negative breast cancer (TNBC)." (PMID 39267843, 2024). "Traditionally, prognostic markers for breast cancer include histological grading, tumor-node-metastasis (TNM) staging, and molecular profiling, such as the expression of estrogen receptor (ER), progesterone receptor (PR), and human epidermal growth factor receptor 2 (HER2)." (PMID 39469410, 2024). "Triple-negative breast cancer is an aggressive subtype of breast cancer characterized by the absence of estrogen receptor, progesterone receptor, and human epidermal growth factor receptor 2 expression." (PMID 38324848, 2024). "The biopsy confirmed the diagnosis of an estrogen receptor-positive status, progesterone receptor-negative status, and Her2-negative status breast carcinoma." (PMID 38730611, 2024).
breast cancer (continued). "Les-6287, Les-6294, and Les-6328 compounds demonstrated high metabolic inhibitory activity towards breast carcinoma MCF-7, T-47D, MDA-MB-231, 4T1, and HCC1954 cells of different types (estrogen and progesterone receptor-positive, triple-negative, and HER2-positive, respectively)." (PMID 39199694, 2024). "Triple-negative breast cancer (TNBC) is an aggressive type of breast cancer that lacks the expression of estrogen receptor (ER), progesterone receptor (PR) and human epidermal growth factor receptor 2 (HER2)." (PMID 37241035, 2023). "Most men with breast cancer are diagnosed with invasive ductal carcinoma, and their tumors are estrogen-receptor (ER) positive, progesterone-receptor (PR) positive, and HER2 negative." (PMID 37685859, 2023). "TNBC is characterized by the absence of the estrogen receptor alpha, progesterone receptor, and the human epidermal growth factor receptor 2, limiting those viable treatment options available to patients with other breast cancer subtypes." (PMID 37835396, 2023). "NUPR1 could also active autophagy and bind to the promoter regions of some autophagy-related genes, such as BECN1, GREB1, RAB31, PGR, CYP1B1, thereby regulating breast cancer metastasis and transcription." (PMID 37626099, 2023). "Based on the expression status of estrogen receptor (ER), progesterone receptor (PR), and human epidermal growth factor receptor 2 (HER2), breast cancer is generally classified into four subtypes: Luminal A, Luminal B, HER2-enriched, and triple-negative breast cancer (TNBC)." (PMID 37454220, 2023). "High TRIP6 mRNA expression was observed in premenopausal (p = 0.033) and progesterone receptor positive (p = 0.020) breast cancer in the adjuvant cohort of breast cancer patients but not in the neoadjuvant cohort (p = 0.50 and p = 0.77, respectively)." (PMID 36833223, 2023). "Different from other breast cancers, TNBC cells lack other receptors, such as the estrogen receptor (ER), progesterone receptor (PR), and human epidermal growth factor receptor (HER-2), which have been proven to be important targets in other breast cancer treatments." (PMID 36986473, 2023). "Triple negative breast cancer (TNBC) is a subtype of breast cancer defined by negative expression of estrogen receptor, progesterone receptor and human epidermal growth factor receptor-2." (PMID 36900331, 2023). "Furthermore, mRNA expression analysis of three breast cancer markers (HER2, PGR, and ESR1) revealed relatively high expression in VCL006, VCL008, and VCL012 compared to other cell lines." (PMID 38033642, 2023). "Approximately 10% to 15% of breast cancers do not express hormone receptors [estrogen receptor (ER) or progesterone receptor (PgR)] and are HER2-negative." (PMID 37773077, 2023). "About 15–20% of breast cancers do not express estrogen (ER) or progesterone receptors (PgR) (≤ 1%) or show human epidermal growth factor receptor 2 (HER 2) overexpression or amplification." (PMID 37418056, 2023). "Therefore, current standard-of-care biomarkers such as estrogen receptor (ER), progesterone receptor (PR), and human epidermal growth factor receptor 2 (HER2) provide important prognostic and predictive information in case of breast cancer." (PMID 36980449, 2023). "TNBC refers to breast cancer that is negative for estrogen receptor (ER), progesterone receptor (PR), and human epidermal growth factor receptor expression (HER2)." (PMID 37767092, 2023). "We have used EO771 cells, which is a murine luminal B mammary cancer cell line (estrogen receptor α negative, estrogen receptor β positive, progesterone receptor positive and ErbB2 positive), originally isolated from a spontaneous tumor in a C57BL/6 mouse." (PMID 36978895, 2023). "Multi-parameter genomic assays, such as Oncotype DX and MammaPrint, are being used for patients with hormone receptor-positive (ER+/PgR+) and HER2- early breast cancer who may benefit from adding chemotherapy to adjuvant endocrine therapy." (PMID 37842235, 2023).
breast cancer (continued). "Triple-negative breast cancers (TNBCs) are defined as those breast cancers that do not express the estrogen receptor (ER) or the progesterone receptor (PgR) and lack ERBB2 gene amplification." (PMID 38254917, 2023). "Triple-negative breast cancer (TNBC) is a distinct subtype of breast cancer characterized by the absence of estrogen receptor (ER), progesterone receptor (PR) and human epidermal growth factor receptor 2 (HER2) expression in immunohistochemistry." (PMID 38111587, 2023). "Triple-negative breast cancer (TNBC) is a subtype of breast cancer defined by the lack of expression of Estrogen-Receptor (ER), Progesterone-Receptor (PgR) and Human-Epidermal Growth Factor Receptor-2 (HER2)." (PMID 36982938, 2023). "The basic status of the estrogen receptor (ER), progesterone receptor (PR), cell proliferation marker Ki-67 (ki67), and human epidermal growth factor receptor 2 (HER2) play a crucial role in molecular subtypes classification of breast cancer." (PMID 37379311, 2023). "This study aimed to examine the clinical characteristics and outcomes of patients with estrogen receptor-negative (ER−)/progesterone receptor-positive (PR+) early breast cancer." (PMID 37199804, 2023). "Triple negative breast cancer (TNBC) is a breast cancer that is negative for estrogen receptor, progesterone receptor and proto-oncogene HER2, accounting for 15%-20% of all breast cancers." (PMID 37996880, 2023). "Estrogen receptor-positive and progesterone receptor-negative (ER + /PR-) breast cancer comprise a special type." (PMID 38049758, 2023). "The progesterone receptor (PgR) is clinically considered a complementary marker of hormone dependency in breast cancer because it is driven partly, but not exclusively, by ER-mediated transcriptional events." (PMID 36721218, 2023). "For example, both tumors were mainly composed of epithelial breast cancer cells (EPCAM+) with a similar distribution of hormone receptors (ERBB2 for HER2, ESR1 for estrogen receptor, and PGR for progesterone receptor) and histology markers (CDH1 for E-cadherin)." (PMID 37301892, 2023). "Triple‐negative breast cancer (TNBC) accounts for 15–20% of breast cancers, which is characterized as a subclass that estrogen receptor (ER), progesterone receptor (PR), and human epidermal growth factor receptor‐2 (HER‐2) deficient in the plasma membrane." (PMID 36847599, 2023). "Triple-negative breast cancer (TNBC) refers to breast cancer with negative ER (estrogen receptor), PR (progesterone receptor), and HER2 (human epidermal growth factor receptor 2) expression; TNBC has a high incidence, accounting for 10–20% of breast cancers." (PMID 36959811, 2023). "Triple-negative breast cancer (TNBC) is an aggressive and heterogeneous subtype of breast cancer with poor prognosis, defined by lack of oestrogen receptor (ER), progesterone receptor (PR) and human epidermal growth factor receptor 2 (HER2)." (PMID 37147730, 2023). "Our results indicated that the content of Chol was higher in MB453 and MB231 than in MCF7 cells, indicating that breast cancer cells unresponsive to hormone therapy in the absence of ER and PgR accumulate Chol." (PMID 36983016, 2023). "The different types of breast cancers are identified, then, by the presence or absence of the receptors found on the surface of the cells: the estrogen receptor (ER), the progesterone receptor (PR), and human epidermal growth factor receptor 2 (HER2)." (PMID 37569780, 2023). "Younger women are more prone to getting a more aggressive form of breast cancer, like triple-negative breast cancer (estrogen receptor (ER)/progesterone receptor (PR) negative and human epidermal growth factor receptor 2 (HER2) negative for amplification)." (PMID 38143654, 2023). "Human breast cancers are classified based on endocrine gene expression, including the expression of the estrogen receptor (ER), human epidermal growth receptor 2 (HER2), and progesterone receptor (PR)." (PMID 37958616, 2023).